INS (insulin)
Diseases named in the same sentence as INS in open-access papers (continued):
Sharing a sentence is not in itself a finding about the gene and the disease.
type 2 diabetes (continued). "Studies have shown decreases in β-cell function prior to the augmentation of plasma glucose in normal glucose-tolerant first-degree relatives of type 2 diabetes subjects; in these studies these relatives had normal insulin sensitivity." (PMID 19794883, 2009). "Resistance exercises have been shown to have a significant impact on insulin sensitivity in people with type 2 diabetes." (PMID 20003276, 2009). "Type 2 diabetes is treated in a stepwise manner, progressing from diet and physical activity to oral antidiabetic agents and insulin." (PMID 19568428, 2009). "Elevated IMCL deposition has been observed in obese individuals, obese subjects with type 2 diabetes and insulin resistant subjects." (PMID 19936240, 2009). "The results from this analysis show that in everyday clinical practice, switching to a basal-bolus glargine-based insulin regimen improves glycaemic control in patients with type 1 or type 2 diabetes inadequately controlled on a premix-based insulin regimen." (PMID 19220880, 2009). "Type 2 diabetes is a disease characterized by impaired β-cell secretion of insulin, in combination with resistance to insulin in its target tissues." (PMID 19794883, 2009). "The results of this subgroup analysis of the IMPROVETM study suggest that by intensifying basal insulin regimens to a BIAsp 30 regimen in routine care, glycaemic control can be significantly improved in inadequately controlled patients with type 2 diabetes." (PMID 19504715, 2009). "The incretin effect, which is responsible for up to 50% of the normal release of insulin following oral glucose ingestion, is significantly reduced in Type 2 diabetes, due both to the diabetes itself and to concomitant obesity." (PMID 18959599, 2008). "On the other hand, type 2 diabetes doesnot stop the endogenous insulin supply, but instead it is characterized ininsulin resistance, insulin deficiency, and hyperglycemia." (PMID 18566688, 2008). "Insulin is a central player in maintaining energy balance in our bodies and in type 2 diabetes, where the effect of insulin on its target tissues is diminished." (PMID 18551197, 2008). "It is important also to look at the duration of insulin therapy when considering hypoglycaemia rates in patients with Type 2 diabetes treated with insulin." (PMID 18215172, 2008). "Type 2 diabetes (T2D) is characterized by defects in both insulin sensitivity and beta-cell dysfunction." (PMID 18498634, 2008). "We recently reported that type 2 diabetes risk alleles in TCF7L2, CDKAL1, and SLC30A8 impair proinsulin-to-insulin conversion." (PMID 19088850, 2008). "In an electromagnetically clean environment, Type 1 diabetics require less insulin and Type 2 diabetics have lower levels of plasma glucose." (PMID 18568931, 2008). "Both elevated plasma glucose and insulin, common features of Type 2 diabetes, influence the immune system." (PMID 18290856, 2008). "Treatment in the earlier phases of type 2 diabetes iscomparatively easier than type 1 diabetes because of the existence of more orless internal insulin production." (PMID 18437199, 2008). "The long-standing assumption that insulin should be used as a last-resort intervention during treatment of patients with type 2 diabetes is now being challenged." (PMID 18279520, 2008). "Insulin is the most effective drug available to achieve glycaemic goals in patients with type 2 diabetes." (PMID 18393965, 2008). "Starting a patient with type 2 diabetes on insulin represents a major step in a patient's treatment schedule, and basal insulin is a popular treatment option for insulin initiation." (PMID 18479365, 2008). "In this article, changes in plasma glucose, in response to electromagnetic pollution, for numerous measurements on four subjects—two with Type 1 diabetes taking insulin and two non medicated with Type 2 diabetes—are described." (PMID 18568931, 2008). "Metformin is an oral hypoglycaemic agent that improves insulin action in patients with type-2 diabetes." (PMID 18852875, 2008).
type 2 diabetes (continued). "SUs, such as tolbutamide and glibenclamide (glyburide), are widely used in patients with type 2 diabetes, because they induce insulin secretion independently of the metabolic state of the β-cell." (PMID 18959471, 2008). "Peroxisome proliferator-activated receptor gamma agonists also modulate glucose metabolism and insulin sensitivity, thereby reducing plasma glucose and insulin levels in type 2 diabetes." (PMID 19018263, 2008). "Type 2 diabetes is characterized by insulin resistance of target organs, which is due to impaired insulin signal transduction." (PMID 18551197, 2008). "A very recently published study investigated associations of the type 2 diabetes risk alleles in JAZF1, CDC123/CAMK1D, TSPAN8/LGR5, THADA, ADAMTS9, and NOTCH2 with obesity, insulin sensitivity, and insulin secretion in 4516 Danes." (PMID 18714373, 2008). "Hypoglycemia can be a bothersome, though rarely serious, adverse event in patients with type 2 diabetes who are treated with insulin therapy." (PMID 18279520, 2008). "Such careful tailoring of the insulin dose comes at a price for patients with type 2 diabetes, who report increased scores of depression and lower quality of life scores." (PMID 19143853, 2008). "PPARγ is involved in glucose metabolism throughthe improvement of insulin sensitivity and represents a potential therapeutictarget of type 2 diabetes." (PMID 18584037, 2008). "Remedi and Nichols' study should prompt further clinical studies exploring the possible advantage of such compounds for maintaining an adequate capacity for insulin secretion in type 2 diabetes." (PMID 18959474, 2008). "PPARγ2 is expressedexclusively in adipose tissue and plays a pivotal role in adipocyte differentiation.PPARγ is involved in glucose metabolism through the improvement of insulin sensitivityand represents a potential therapeutic target of type 2 diabetes." (PMID 18584037, 2008). "At the same time, low-dose STZ has been known to induce a mild impairment of insulin secretion which is similar to the feature ofthe later stage of type 2 diabetes." (PMID 19132099, 2008). "Weekly rates of hypoglycaemic episodes have been estimated at 0.82 and 0.33 for persons with Type 1 and insulin-treated Type 2 diabetes, respectively." (PMID 18823555, 2008). "Overall, these datasuggest that one effect of type II diabetes on the β-cellis to promote an aberrant differentiation state in which β-cellslose insulin expression and begin to express exocrine markers." (PMID 19165345, 2008). "Previous studies have proven the beneficial effect of SMBG in patients with type 1 diabetes and in patients with type 2 diabetes who use insulin." (PMID 18501012, 2008). "Less is known about the factors that contribute to physician reluctance to initiate insulin in patients with type 2 diabetes." (PMID 18393965, 2008). "Type 1 diabetics require less insulin in an electromagnetically clean environment and blood sugar levels for Type 2 diabetics increase with increasing exposure to dirty electricity." (PMID 18568931, 2008). "A distinctive feature of type 2 diabetes is inability of insulin-secreting β-cells to properly respond to elevated glucose eventually leading to β-cell failure." (PMID 18478125, 2008). "For example, a growing body of data has demonstrated an association between chronic insulin therapy and development of CRC among patients with type II diabetes mellitus." (PMID 19032772, 2008). "Two-thirds of the PCPs in this study agreed with the statement ‘...the initiation of insulin is one of the most difficult aspects of managing my patients with type 2 diabetes’." (PMID 18393965, 2008). "Impairment in both hepatic and peripheral insulin action, and defective pancreatic insulin secretion characterize fully developed type 2 diabetes." (PMID 18366646, 2008). "Intensifying existing insulin treatment regimens in type 2 diabetes is essential if optimal glycaemic control is to be maintained because of the progressive nature of the disease." (PMID 18479365, 2008).
type 2 diabetes (continued). "It has been reported that SOCS-3 mRNA levels are increased in the skeletal muscle of type 2 diabetic patients compared with control subjects and correlates with reduced insulin-stimulated glucose uptake." (PMID 18941624, 2008). "PPARγ isthe molecular target for the synthetic thiazolidinediones (TZD), such asrosiglitazone and pioglitazone, clinically used as insulin sensitizers inpatients with type 2 diabetes." (PMID 18288288, 2008). "Type 2 diabetes is a multifactorial disease characterised by chronic hyperglycaemia resulting from defects in insulin secretion and/or insulin action." (PMID 18489578, 2008). "Fourteen patients with type II diabetes mellitus and on insulin treatment, presenting diffuse cystoid macular edema were recruited." (PMID 18366650, 2008). "Hypoglycaemia is a common unintended consequence of insulin that ranges from being bothersome to resulting in coma or even death among persons with diabetes." (PMID 18823555, 2008). "Type 2 diabetes characterized by target-tissue resistance to insulin, is epidemic in industrialized societies and is strongly associated with obesity." (PMID 21876654, 2008). "Accordingly, sulfonylureas, a group of insulin secretagogues, have long been cornerstones in the pharmacological treatment of type 2 diabetes." (PMID 18959474, 2008). "The aim of this analysis was to assess the efficacy and safety of intensifying insulin therapy from a basal-only regimen to biphasic insulin aspart 30 (BIAsp 30) in patients with type 2 diabetes previously failing to reach glycaemic targets." (PMID 18479365, 2008). "Fasting and postprandial glycemia both are abnormal in type 2 diabetes, and the basal-bolus insulin strategy most closely resembles normal physiologic patterns." (PMID 18279520, 2008). "Impaired insulin-stimulated glycogen synthesis, which is a feature of insulin-resistant muscle and liver cells, is thought to be a key event in the development of type 2 diabetes." (PMID 18232732, 2008). "For example, insulin, which is hypersecretedat early stages in type II diabetes in response to end organ unresponsiveness,is a potent inhibitor of GSK3 and thus a potential activator of the Wnt pathway." (PMID 19165345, 2008). "A coding non-synonymous polymorphism of SLC30A8 (R325W; rs13266634) has been demonstrated to be protective for type 2 diabetes and was shown to influence insulin secretion following an intravenous glucose challenge." (PMID 19096518, 2008). "Glucagon-like peptide-1 (GLP-1) is an enteric hormone that stimulates insulin secretion and improves glycaemia in type 2 diabetes." (PMID 19041768, 2008). "As the KLF11 gene is one of the key regulators in insulin secretion, we considered KLF11 to be an important candidate gene for Type 2 diabetes and systematically surveyed the genetic variants." (PMID 18199129, 2008). "We would like to examine the best way of treating LADA in the early phase of the conditions, with tablets (similar to type 2 diabetes) or with insulin (similar to type 1 diabetes)." (PMID 18652676, 2008). "Recently, RBP4 levels have been reported to be elevated in insulin resistant subjects as well as in subjects with obesity and type 2 diabetes (T2DM)." (PMID 18752671, 2008). "In January 2006 the US Food and Drug Administration (FDA) approved an inhaled powder form of recombinant human insulin for the prandial treatment of adult patients with type 1 and type 2 diabetes." (PMID 18279520, 2008). "Subjects in the present study displayed IGT where insulin secretion was relatively maintained, and a similar study is needed in patients with type 2 diabetes where insulin secretion is somewhat depressed." (PMID 18633754, 2008). "Data derived from the DARTS-MEMO databases have revealed that 7.3% of patients with Type 2 diabetes treated with insulin suffered at least one episode of severe hypoglycaemia—a comparable figure to patients with Type 1 diabetes treated with insulin (7.1%)." (PMID 18215172, 2008).
type 2 diabetes (continued). "Casp8 (caspase 8) is essential for ß cell apoptosis in type 1 and type 2 diabetes models and in regulating ß cell mass and insulin secretion under physiological conditions." (PMID 19471607, 2008). "Type 1 diabetes results from autoimmune-mediated destruction of β cells in the islets of Langerhans of the pancreas, while type 2 diabetes is due to systemic insulin resistance and reduced insulin secretion by islet β cells." (PMID 18298656, 2008). "Type 2 diabetes is a progressive disease characterized by defects in insulin secretion and utilization." (PMID 18279520, 2008). "Epidemiological data suggest that the incidence of hypoglycaemia in patients with Type 2 diabetes is highest when patients are using insulin." (PMID 18215172, 2008). "Insulin resistance in muscle, adipose, and liver tissues and impaired insulin secretion from pancreatic β cells contribute to the pathogenesis of type 2 diabetes (T2D)." (PMID 18366806, 2008). "After the DCCT and Kumamoto study that demonstrated the efficacy of insulin therapy in type 1 and type 2 diabetes, the advent of biphasic insulin formulations has added to the diversity of insulin regimens available." (PMID 18507868, 2008). "HI is also often present at the onset of clinically overt type 2 diabetes, which is interpreted as the endocrine pancreas trying to compensate for primary defects in insulin sensitivity in the peripheral tissues." (PMID 18959471, 2008). "In the light of the potential role of KLF11 in insulin action, we present a detailed re-examination of the KLF11 variants and test the possible association with Type 2 diabetes in 1818 Japanese participants." (PMID 18199129, 2008). "Type 2 diabetes mellitus (T2D) is a heterogeneous disease characterized by different degrees of insulin resistance and defects in insulin secretion, both of which are thought to result from the interplay of genetic and environmental factors." (PMID 19055834, 2008). "Patients with type 2 diabetes chronically treated with SUs often progress to a failure of β-cells to secrete insulin." (PMID 18959471, 2008). "Regular physical exercise has been reported to be effective in the prevention and delay of onset of type 2 diabetes, increases insulin sensitivity, and ameliorates glucose metabolism." (PMID 18477407, 2008). "PI3K/Akt pathway is one of the signaling cascades activated by insulin and plays a major role in hepatic glucose homeostasis, and Akt knockout mice show insulin resistance that later developed to a phenotype of type 2 diabetes." (PMID 19114996, 2008). "In type 2 diabetes, tissues become insulin resistant, the ability of the pancreatic β cells to secrete insulin is impaired, and β-cell function declines progressively over time." (PMID 18279520, 2008). "Although severe hypoglycemia is relatively rare in type 2 diabetes, even among patients on insulin therapy, these events can occur." (PMID 17448241, 2007). "Subjects with type 2 diabetes showed a slight improvement in insulin sensitivity, but postprandial blood glucose and insulin levels were not affected when apple cider vinegar was added to a meal." (PMID 18093343, 2007). "Complete questionnaires were available from 282 type 2 diabetes, of whom 136 (48%) were insulin treated." (PMID 18096074, 2007). "Data from this sample of US type 2 diabetes revealed some interesting differences between insulin-naïve and insulin-treated patients, suggesting a trend towards a less negative appraisal of insulin therapy in those who actually are on insulin treatment." (PMID 18096074, 2007). "This review provides practical recommendations for initiating basal and basal-prandial insulin therapy in type 2 diabetes, with a focus on insulin analogs." (PMID 17448241, 2007). "To assess the appraisal of insulin therapy of persons with type 2 diabetes, we developed the insulin treatment appraisal scale (ITAS) and tested its reliability and validity in insulin treated type 2 diabetes patients." (PMID 18096074, 2007).